EIF1B (eukaryotic translation initiation factor 1B)
Description:
Probably involved in translation.
Synonyms: GC20
Tractability: PROTAC: ubiquitination databases record sites on it.
Gene: Protein-coding gene on chromosome 3 (40,309,707 to 40,312,424, forward strand). Ensembl gene ENSG00000114784.
Gene Ontology:
Molecular function: protein binding; RNA binding; ribosomal small subunit binding; translation initiation factor activity
Biological process: regulation of translational initiation; regulation of gene expression; translational initiation
Cellular component: eukaryotic 43S preinitiation complex
Genetic constraint (gnomAD): Loss-of-function variants: 4 observed, 11.44 expected, observed/expected ratio (o/e) 0.35, 90% interval 0.17 to 0.8. The upper end of that interval is the gene's LOEUF score, 0.8, which puts it in group 3 of 6, group 1 being the genes least tolerant of losing a copy. Missense variants: 48 observed, 122.07 expected, observed/expected ratio (o/e) 0.39, 90% interval 0.31 to 0.5. Synonymous variants: 41 observed, 42.93 expected, observed/expected ratio (o/e) 0.96, 90% interval 0.74 to 1.24.
Homologues: Orthologues: chimpanzee EIF1B (100% identical), dog EIF1B (100% identical), guinea pig EIF1B (100% identical), macaque EIF1B (100% identical), mouse Eif1b (100% identical), pig EIF1B (100% identical), tropical clawed frog eif1b (96% identical), zebrafish eif1b (96% identical), rat Eif1b (92% identical), Caenorhabditis elegans eif-1 (50% identical). Paralogues in human: EIF1 (92% identical).
Diseases named in the same sentence as EIF1B in open-access papers:
EIF1B is named in the same sentence as 4 diseases in open-access papers, as found by Europe PMC text mining. Sharing a sentence is not in itself a finding about the gene and the disease. The quoted sentences say what the papers report.
mixed cell uveal melanoma (1 paper, 2025). A melanoma arising from the choroid, ciliary body, or the iris. "EIF1B is a translation regulator that is an oncogene in mixed-cell uveal melanoma." (PMID 41347211, 2025).
uveal melanoma (1 paper, 2021). A melanoma derived from melanocytes of the uveal tract. "Harbour and coworkers described a 12 genes expression profile predictive of systemic metastasis in uveal melanoma including EIF1B." (PMID 34434692, 2021).
EIF1B also shares sentences with these, for which no sentence is quoted: cancer (3 papers); tumor (1).